LAMP2 (lysosome associated membrane protein 2)
Diseases named in the same sentence as LAMP2 in open-access papers (continued):
Sharing a sentence is not in itself a finding about the gene and the disease.
tumor (continued). "Superposition of the acidity map from SNARF-1 with IHC staining was then used to correlate the expression level LAMP2 in different regions of the tumour with different pHe values." (PMID 26658462, 2015). "In vivo, short hairpin RNA (shRNA) knockdown of LAMP2 in acid-adapted cells induced a lag period before commencement of tumour growth." (PMID 26658462, 2015). "Other research indicated an increased expression of LAMP-1 and LAMP-2 on the surfaces of highly metastatic cells, specifically those associated with metastatic CRC, which the authors correlated with tumor progression and the acquisition of metastatic characteristics." (PMID 40277899, 2025). "Following cryoablation, pHe values within the tumor shifted toward physiological neutrality, accompanied by histopathologic evidence of decreased expression of hexokinase-2 (HK2) and lysosome-associated membrane protein 2 (LAMP-2), indicating downregulation of glycolytic flux and lysosomal activity." (PMID 41377976, 2025). "Higher CAIX and LAMP2 protein expression levels were also detected in 4T1 tumors (p < 0.01 and p < 0.05, respectively), which is in line with the results of pimonidazole and LAMP2 IF staining, thus confirming the observed in vivo results on tumor acidosis." (PMID 40551171, 2025). "It was reported that LAMP2 also played a central role in tumor cell metastasis." (PMID 37986192, 2023). "Moreover, we found the expression of LAMP2 was dramatically decreased in xenografted tumor tissue from mice injected with TSTA3 overexpressing LUSC cells compared with control cells." (PMID 37986192, 2023). "In summary, LAMP2 is related to immune modulatory factors in a variety of tumor types." (PMID 35530327, 2022). "LAMP2, a single transmembrane protein located on the restriction endosomal membranes of lysosomes and advanced nuclear nucleosomes, has an important role in tumor cell metastasis in EAC." (PMID 35530327, 2022). "The present study provides some new evidence that a high expression of LAMP2 in tumor cells may induce tumor growth and metastasis through the formation of a hypoxic microenvironment and ER stress." (PMID 35530327, 2022). "Necrosis, glucose uptake, and tissue acidosis within the tumor were confirmed with histopathological markers that showed increased expression of glucose transporter 1 (GLUT-1) and lysosome-associated membrane protein 2 (LAMP-2))." (PMID 36589457, 2022). "In addition to its expression on the lysosomal membrane, LAMP2 is reportedly relocalized to the cell surface of some highly metastatic tumor cells, such as melanoma and colon cancer cells." (PMID 32295144, 2020). "In HCC, LAMP2 is required for tumor growth and promotes tumor recurrence." (PMID 32295144, 2020). "Also, the mRNA levels of Map1lc3b and Sqstm1 were upregulated in tumor hosts, together with increased Ctsl1 and Lamp2 gene expression." (PMID 30823492, 2019). "Furthermore, multivariate Cox regression analysis indicated that the Lamp2 expression level, tumor diameter, tumor number, and microvascular invasion were correlated with both the RFS and OS." (PMID 30100986, 2018). "Similarly, IL8 localized very closely to the LAMP2-positive tumor area, but with only a partial overlap (third string), possibly because IL8 is secreted close to the acidic area of the BM microenvironment and mostly by untransformed mesenchymal stromal cells." (PMID 28903357, 2017). "The authors explain the overexpression of LAMP2 as an adaptation mechanism to chronic acidosis in the tumor microenvironment, since depletion of LAMP2 is sufficient to increase acidosis-mediated toxicity and, interestingly, tap-water bicarbonate sodium therapy reduces LAMP2 expression." (PMID 27627761, 2016). "A key experiment to test whether LAMP2 is a marker of acidosis was performed by treating animals with oral buffers, for example, sodium bicarbonate (NaHCO3), which are known to neutralize tumour acidity." (PMID 26658462, 2015).
tumor (continued). "We consistently saw high LAMP2 staining in regions of tumours expected to be acidic, such as the peri-luminal region of DCIS and cells in areas of microinvasion, which are consistent with our previous observation in DWC experiments that invasion is stimulated by acidosis." (PMID 26658462, 2015). "Additionally, ex vivo immunohistochemistry for LAMP2 revealed a stronger signal in 4T1 tumors within the whole section, which was also observed to be closer to necrotic areas, whereas 67NR tumors presented less signal mainly found at tumor boundaries." (PMID 40551171, 2025). "The genes most positively associated with TMBIM6 expression, including LAMP2, APLP2, TMED10, PPAPDC2, ZNF652, and CTSB, are primarily involved in lysosomal and ER trafficking, membrane dynamics, and metabolic resilience—pathways that facilitate tumor survival under cellular stress conditions." (PMID 41516091, 2025). "LAMP2 was evaluated ex vivo via immunofluorescence and was found to be significantly increased in 4T1 tumors than in 67NR ones, which can be related to the CEST results for tumor pHe and may be associated with increased tumor aggressiveness." (PMID 40551171, 2025). "In our study, we demonstrated that NDV infection causes post-transcriptional degradation of both LAMP1 and LAMP2 proteins in various tumor and avian cells, while it does not significantly affect the expression of other lysosomal membrane proteins including LAMP3, LIMP II, and LAPTM5." (PMID 38354122, 2024). "However, to confirm this hypothesis, it is necessary to conduct additional studies of LAMP-2 expression patterns at the level of mRNA and proteins in various tumor tissues, as well as in embryonic tissues at various stages of development." (PMID 36830954, 2023). "However, an alternative hypothesis could be that unrestrained lysosomal exocytosis is the culprit that drives both the redistribution of LAMP2 at the PM and contributes to the acidification of the tumor microenvironment." (PMID 33718382, 2021). "Furthermore, LAMP2 expression in Ogr1fl/flCD8Cre+/− mice was also at a low level, which indicated that the inactivation of Ogr1 in T cells attenuated the acidification of the tumor environment." (PMID 34158625, 2021). "Our study showed the highest level of LAMP-2 transcriptional activity in the clinical stage II of CRC, suggesting that the CMA process has a tumor-inhibitory effect in the later stages of the disease." (PMID 36830954, 2023). "At the same time, there were significant differences in the expression of these genes in tumor samples and normal samples, with the exception of TP63, KLHL24, and LAMP2, which were all downregulated in tumors." (PMID 36147441, 2022). "Our results show that LAMP2 expression in ESCA and other tumors is positively correlated with tumor-infiltrating immune cells." (PMID 35530327, 2022). "For instance, one study in breast cancer reports the presence of LAMP2, a LAMP1 homologous protein, at the PM of tumor cells located at the invasive front." (PMID 33718382, 2021). "In contrast, CCL17 expression was greatly increased in tumor tissues from mice in the GH3+M0+LA group, similar to LDHA and Lamp2 levels, compared with samples from the control and untreated groups." (PMID 33664865, 2021). "The expression of lysosomal-associated membrane protein 2 (LAMP2) is positively correlated with tumor microenvironment acidity, and we found that VDR expression and LAMP2 expression in CRC were negatively correlated." (PMID 32900990, 2020). "Together, our findings clearly indicate that FAM215A increases tumor progression and DOX resistance in HCC by interacting with and increasing the stability of LAMP2." (PMID 32295144, 2020). "We found a proportionate relocation of LAMP2 to the plasma membrane of LN229 acid-adapted cells, wherein high surface localization was observed in tumor cells exposed to low and very low pH." (PMID 28299282, 2017).
tumor (continued). "The results showed a decreased intensity of LAMP2 and VAMP8 in cells and tumor tissues of shERRα." (PMID 39820331, 2025). "At higher concentrations, autophagy and lysosome biogenesis genes, such as SQSTM1/p62, LAMP2, and PINK1, were robustly upregulated along with tumor suppressors, such as PTEN, and pro-apoptotic factors, including BAD and BIK, which reinforce autophagic flux and promote cellular homeostasis." (PMID 40671124, 2025). "To confirm the correlation between tumor acidosis and metabolic alterations, and indeed their relationship with a malignant phenotype, we evaluated glycolysis markers such as LDH-A and PDK-1, in addition to LAMP2 and CAIX, which are involved in both tumor acidosis and hypoxia." (PMID 40551171, 2025). "We found that the mRNA expressions of LDHA (p = 0.038) and LAMP2 (p < 0.0001) were significantly higher in tumor tissues compared to the adjacent nontumor tissues." (PMID 38136340, 2023). "We used qRT-PCR to quantify the expression of LA-related genes (LDHA and LAMP2) in CRC tumor tissues and adjacent nontumor tissues (n = 64)." (PMID 38136340, 2023). "To investigate whether lactic acid is responsible for tumor invasion in PAs, we measured the levels of LDHA and LAMP2 expression in noninvasive human PAs (n = 32) by qRT-PCR and compared them with those in invasive PA samples (n = 32)." (PMID 33664865, 2021). "On the other hand, LAMP2 expression in plasma membranes has been detected in blood and tumor cells and we cannot rule out increased expression of LAMP2 in NE cells plasma membrane." (PMID 27627761, 2016). "Specifically, LAMP2 expression was higher in the Her2 molecular subtype of BRCA, the CIN molecular subtype of COAD, HM-SNV molecular subtype of STAD, iCluster:2 molecular subtype of LIHC, and ESCC subtype of ESCA compared with the other molecular subtypes of the respective tumor types." (PMID 35530327, 2022). "Further, significantly high expression and colocalization of LAMP2 and surface cholesterol were detected in necrotic and pseudo-palisading zones of GBM patient samples, followed by moderate expression and colocalization in ‘Cellular Tumor’ zone vs. the leading edge areas." (PMID 28299282, 2017). "Knowing that early tumour xenografts are acidic due to lack of vasculature leads us to test whether LAMP2 is critical for growth of early tumours." (PMID 26658462, 2015). "In this regard and due to the presence of LAMP2 or other endosome markers as Rab5 (see PXD030936), we can speculate that RBCs from metastatic BC patients could maintain a modified endosomal–lysosomal system which would support protein turnover as a reservoir of amino acids for tumor cells." (PMID 36519745, 2022).
myopathy (13 papers, 2015 to 2026). A disease of the muscle in which the muscle fibers do not function properly. "The pathological hallmark of this disease is an accumulation of glycogen and autophagic vacuoles in cardiac and skeletal muscle that, along with the myopathy, is also present in LAMP-2-deficient mice." (PMID 25637286, 2015). "In the absence of LAMP2, fusion of autophagosomes with lysosomes is blocked, leading to accumulation of long-lived proteins and consequent myopathy." (PMID 27551448, 2015). "However, less than 50% of LAMP2 expression was detected in the II 3 individual; thus the absence of myopathy may be attributed to other factors as well." (PMID 31464081, 2019).
neurodegenerative disease (7 papers, 2014 to 2024). A disorder of the central nervous system characterized by gradual and progressive loss of neural tissue and neurologic function. "Further explorations in prospective studies, larger cohorts and/or of biomarker disease specificity are required to determine the relevance of the level of LAMP2 as a measure reflecting the neuropathology of AD or other neurodegenerative diseases." (PMID 26924951, 2016).
renal disease (5 papers, 2020 to 2024). "Although the prevalence of LAMP-2-ANCA has been debated in PR3/MPO-ANCA-associated vasculitis (AAV) and AAV-related kidney disease, overlapping seropositivity for LAMP-2-ANCA with MPO- or PR3-ANCA in SVV is consistently observed." (PMID 38612581, 2024). "Unlike MPO or PR3, a lesser known ANCA antigen, LAMP-2, is expressed on the surface of the renal microvascular endothelium and LAMP-2-ANCA have been detected in adults with AAV-associated renal disease." (PMID 33613565, 2020). "Renal disease is a common manifestation in systemic small-medium vessel vasculitis (both in adults and children, though more severe in children) and our preliminary data suggest LAMP-2-ANCA at diagnosis may be a risk factor for more severe renal disease." (PMID 33613565, 2020). "Alterations in LAMP2 expression and function have been observed in kidney diseases." (PMID 38536018, 2024). "In the highest reported prevalence rate of LAMP-2-ANCA in >80% of adults with AAV-associated renal disease, a recombinant, non-glycosylated human LAMP-2 protein was utilized in the immunoassays." (PMID 33613565, 2020). "Similarly, there is a trending increase in LAMP-2-ANCA titers in patients with worsening renal disease at 12 months, as determined by a decrease in GFR > 10 ml/min/1.73m2." (PMID 33613565, 2020). "Increasing LAMP-2-ANCA titers were observed in patients with declining glomerular filtration rate (GFR), indicative of worsening renal disease one-year post diagnosis." (PMID 33613565, 2020).
heart diseases (3 papers, 2016 to 2022). "In addition, among the family members suspected of carrying the LAMP2 mutation, only two female members were diagnosed with heart disease and one of them died suddenly." (PMID 33933120, 2021).
Metabolic disorders (3 papers, 2020 to 2025). "Associations with nutritional and metabolic diseases were also less important, and were mainly linked to the genes RMST, HK1, HLA-DQA1 and LAMP2." (PMID 36430729, 2022).
adenocarcinoma (2 papers, 2022 to 2023). A common cancer characterized by the presence of malignant glandular cells. "High LAMP2 expression, adenocarcinoma, and a history of alcohol use were significantly correlated with worse OS and DSS." (PMID 35530327, 2022).
bacterial infection (2 papers, 2020 to 2025). "While more research results are needed to provide a definitive conclusion on the effect of Lamp2 on bacterial infection, some studies have suggested that Lamp2 plays a role in lysosomal function and autophagic flux, which are essential for the degradation of cellular waste and pathogens." (PMID 40076623, 2025). "In particular, given the molecular mimicry hypothesis, an individual with a previous Type I fimbriated bacterial infection could theoretically develop antibodies to LAMP-2." (PMID 33613565, 2020).
cardiovascular disease (2 papers, 2018 to 2021). "Among cardiovascular disease-relevant, differentially methylated genes in males, Atg5, Ank2, Cux1 and Lamp2 exhibited significant increases in gene expression." (PMID 33445541, 2021). "Mutations of the following genes can lead to cardiovascular disease: Filamin A, EMD (emerin), LAMP2 (lysosomal-associated membrane protein 2), DMD (dystrophin), TAZ (tafazzin), and VEGF-D (vascular endothelial growth factor D)." (PMID 30459711, 2018).
cerebral artery (1 paper, 2021). "In cases of middle cerebral artery occlusion, adjacent to the occlusion were reactive astrocytes which were positive for neuronal debris which was colocalized with the Lysosomal Associated Membrane Protein 2 (LAMP2)." (PMID 33803137, 2021).
neurological disorders (1 paper, 2020). "In addition, it will be interesting to examine LAMP2- and HS-related phenotypes in iAs, due to the important role of astrocytes in neurological disorders and the potential of SRT targeting EXTL2 and EXTL3 in iAs." (PMID 32121121, 2020).
vasculopathy (1 paper, 2018). "We assume that at least three factors contribute to the pathogenesis of vasculopathy under LAMP-2 deficiency." (PMID 29463847, 2018). "The present study aimed to clarify the clinical and biological features of vasculopathy under LAMP-2 deficiency." (PMID 29463847, 2018). "Thus, tissue-specific variability in relative LAMP protein abundance may modulate the vascular phenotypes; the tissues in which alternate LAMP-1 upregulation can not compensate for the defective LAMP-2 in VMSC are more susceptible to injury leading to vasculopathy." (PMID 29463847, 2018).
LAMP2 also shares sentences with these, for which no sentence is quoted: Fabry disease (6 papers); Intellectual disability (6); Skeletal myopathy (6); heart failure (4); Autoimmunity (3); COVID-19 (3); esophageal squamous cell carcinoma (3); genetic disorder (3); retinopathy (3); esophageal cancer (2); familial hypertrophic cardiomyopathy (2); fibrosarcoma (2); fibrosis (2); hematological diseases (2); infectious disease (2); renal cell carcinoma (2); Takayasu arteritis (2); acute lymphoblastic leukemia (1); acute respiratory distress syndrome (1); allergic rhinitis (1); ameloblastoma (1); amyloidosis (1); anemia (1); Barth syndrome (1); blood cancer (1); calcification (1); cardiac amyloidosis (1); Carvajal syndrome (1); cerebral infarction (1); cervical cancer (1).
A further 75 diseases each share a sentence with LAMP2 in 1 paper.